DNMT3A (DNA methyltransferase 3 alpha)
Diseases named in the same sentence as DNMT3A in open-access papers (continued):
Sharing a sentence is not in itself a finding about the gene and the disease.
cutaneous T-cell lymphomas (1 paper, 2023). "Although both cell lines (HuT78 and HH) derived from CD4+ cutaneous T-cell lymphomas are probably similar to normal CD4+ T cells, they lack mutations in TET2, DNMT3A, and IDH2 in contrast with the neoplastic cells of AITL." (PMID 37370838, 2023).
diabetic polyneuropathy (1 paper, 2023). "They suggested that the conflicting action of DNMT3A and TET2 in DNA methylation and hematopoietic stem cell differentiation might explain their opposite association with diabetic polyneuropathy." (PMID 36807865, 2023).
eczema (1 paper, 2025). "Further accumulation of cases will be needed to clarify whether eczema and elevated IgE represent coincidental comorbidities or reflect a broader, incompletely defined spectrum of DNMT3A-related disease." (PMID 41384217, 2025).
erythroleukemia (1 paper, 2021). Acute erythroid leukemia characterised by the presence of at least 50% erythroid precursors and at least 20% myeloblasts in the bone marrow.
fibroepithelial polyp (1 paper, 2025). A polypoid lesion composed of fibrous tissue and epithelium. "The other mutations found in our case (DNMT3A, C8B, TET2, SDHA, ARID1B, NOTCH1, OR5L1, and KDM6A) do not have a known association with the formation of fibroepithelial polyps." (PMID 40936011, 2025).
gestational diabetes mellitus (1 paper, 2021). "Increased ROS levels have been reported in gestational diabetes mellitus (GDM) model and this has caused a global DNA methylation by increasing DNA methyltransferase (DNMT3A)." (PMID 35008847, 2021).
graft versus host disease (1 paper, 2025). An immune system disorder that occurs after allogeneic hematopoietic stem cell transplant and is a reaction of donor immune cells against host tissues. "The specific impact of DNMT3A mutations in allogeneic stem cell transplantation is unclear, although clinical data suggest that donor DNMT3A mutations are associated with increased graft-versus-host disease, reduced recurrence, and improved survival." (PMID 39078434, 2025).
granular cell tumor (1 paper, 2021). An unusual benign or malignant neoplasm characterized by the presence of neoplastic large polygonal cells with granular, eosinophilic cytoplasm which contains abundant lysosomes. "Within the 10 sequenced granular cell tumors, we only detected a single case with a driver variant (in the epigenetic regulator DNMT3A)." (PMID 34661724, 2021).
Granuloma (1 paper, 2020). A compact, organized collection of mature mononuclear phagocytes, which may be but is not necessarily accompanied by accessory features such as necrosis. "Expression levels of the DNMT3A, B and TET1 and 2 genes did not correlate with number and volume of granulomas." (PMID 32078636, 2020).
head and neck paraganglioma (1 paper, 2020). A benign or malignant extra-adrenal paraganglioma arising from paraganglia in the head and neck. "We recently found germline DNMT3A gain-of-function variants in two patients with head and neck paragangliomas causing a characteristic hypermethylated DNA profile." (PMID 33182397, 2020).
hearing disorder (1 paper, 2018). A disorder characterized by the partial or complete loss of the ability to detect sounds due to damage to the ear structures or inability of the brain to properly interpret or process the auditory signals it receives from the anatomic structures of the ear. "However, considering the vital roles of DNMT1 in hearing disorders and of DNMT3A in oxidative stress, we speculated that polymorphisms in DNMT1, DNMT3A and their interactions could be associated with genetic susceptibility to NIHL." (PMID 30111769, 2018).
hemangioma (1 paper, 2024). A benign vascular lesion characterized by the formation of capillary-sized or cavernous vascular channels. "The combination of DNMT3A inhibition and miR-206 overexpression has been shown to promote extracellular matrix deposition and impede malignant transformation of hemangioma endothelial cells, suggesting a potential therapeutic approach." (PMID 38826780, 2024).
hepatoblastoma (1 paper, 2019). Hepatoblastoma (HB) is a malignant hepatic tumor and is the most common pediatric liver cancer. "Therefore, it is possible that DNMT1 and DNMT3A upregulation observed in the present study contributes to the hypermethylation at specific CpG islands we previously reported in hepatoblastomas." (PMID 31249594, 2019).
hypercoagulability (1 paper, 2025). "In addition to JAK2, mutations in TET2 and DNMT3A play critical roles in CHIP-mediated hypercoagulability." (PMID 40141381, 2025). "CHIP is characterized by the expansion of hematopoietic stem cell clones harboring somatic mutations in genes such as TET2, DNMT3A, and ASXL1, which are implicated in inflammation, atrial remodeling, and hypercoagulability." (PMID 40141381, 2025).
Hyperinsulinemia (1 paper, 2022). An increased concentration of insulin in the blood. "Our results demonstrated that the intrauterine hyperinsulinemia environment has increased hepatic FoxO1 levels and subsequently increased expression of DNMT3A and epigenetic alterations on IGF2/H19 DMRs." (PMID 35432202, 2022). "In conclusion, our study demonstrated that intrauterine hyperinsulinemia increased hepatic FoxO1 levels and contributed to the upregulation of DNMT3A, subsequently inducing the downregulation of IGF2/H19 expression in the liver of GDM-F1 mice." (PMID 35432202, 2022).
intestinal tumors (1 paper, 2010). "It was therefore necessary to quantify the ratio of the functional Dnmt3a 2lox allele (2lox) and the truncated Dnmt3a 1lox allele (1lox) in the intestinal mucosa and in intestinal tumors of transgenic mice." (PMID 20950424, 2010).
ischemic stroke (1 paper, 2024). A stroke disorder caused by obstruction of blood flow to the brain, due to thrombotic (local blood clot formation) or embolic (due to a blood clot or other material traveling from another site) event. "In conclusion, our study provides evidence that DNMT3A dysfunction is associated with neurological functional disability in ischemic stroke patients and mice." (PMID 39006763, 2024). "In a well‐characterized cohort of 8524 ischemic stroke patients, we demonstrated that DNMT3A‐driven CHIP was significantly associated with neurological disability in these patients." (PMID 39006763, 2024). "Our findings showed that inhibition of DNMT3A function increased peripheral blood neutrophils and caused brain neutrophil infiltration after ischemic stroke, which is consistent with the RNA sequencing results." (PMID 39006763, 2024). "•Evaluate the association of DNMT3A‐driven clonal hematopoiesis and worse neurological functional disability in ischemic stroke patients in a well‐characterized cohort of 8524 patients with AIS." (PMID 39006763, 2024).
Kabuki syndrome (1 paper, 2021). Kabuki syndrome (KS) is a multiple congenital anomaly syndrome characterized by typical facial features, skeletal anomalies, mild to moderate intellectual disability and postnatal growth deficiency. "Methyltransferases have been shown to be responsible for episignatures in other neurodevelopmental disorders, e.g., DNMT3A in patients with Tatton–Brown–Rahman syndrome and KMT2D in Kabuki syndrome." (PMID 34445317, 2021).
keloid (1 paper, 2025). An irregularly shaped, elevated mark on the skin caused by deposits of excessive amounts of collagen during wound healing. "What’s more, IFNγ has a synergistic relationship with DNMT3A in keloids." (PMID 39820341, 2025). "To reveal the relationship between IFNγ and DNMT3A, we hypothesized the DNMT family induced hypermethylation of IFNγ promoter in keloid so as to decrease its expression." (PMID 39820341, 2025).
knee osteoarthritis (1 paper, 2022). "A matched case-control study showed that DNMT1, DNMT3A, and DNMT3B gene polymorphisms are significantly associated with radioactive primary knee osteoarthritis." (PMID 35747513, 2022).
laryngeal squamous cell carcinoma (1 paper, 2025). A squamous cell carcinoma that arises from the larynx. "Low expression of DNMT3A and positive N-status were associated with disease-specific mortality in patients with advanced stage laryngeal squamous cell carcinoma primarily treated with radiotherapy." (PMID 40507223, 2025).
leiomyoma (1 paper, 2022). A well-circumscribed benign smooth muscle neoplasm characterized by the presence of spindle cells with cigar-shaped nuclei, interlacing fascicles, and a whorled pattern. "CBX4 also acts as a SUMO-E3 ligase for modulation of the activity and stability of DNMT3A, which is overexpressed in leiomyomas." (PMID 35641855, 2022).
lung neoplasm (1 paper, 2018). A benign or malignant, primary or metastatic neoplasm involving the lungs. "It is observed that the density distribution of purine/pyrimidine is balanced for hh2220 and h616 and they target to DNMT3A causing the disease Lung Neoplasms." (PMID 29967426, 2018).
metastasis (1 paper, 2024). The spread or migration of cancer cells from one part of the body (where they first appeared) to another. "The results showed that GBC tissues from patients with liver metastasis had higher DNMT3A and YAP expression but lower CDH1 expression than those from patients without liver metastasis." (PMID 38380551, 2024).
methicillin-resistant (1 paper, 2021). "Genetic variants of a prototypical DNA methyltransferase encoded by DNMT3A were demonstrated to alter macrophage function in vitro, as well as the host response in a murine model of methicillin-resistant Staphylococcus aureus bacteremia." (PMID 34399830, 2021).
mitral valve prolapse (1 paper, 2024). A fairly common and often benign valvular heart disorder characterized by redundancy or hooding of mitral valve leaflets so that they prolapse into the left atrium, often causing mitral regurgitation. "This article presents a rare case of TBRS attributable to a novel mutation in the DNMT3A gene, which is characterized by mitral annular separation with associated mitral valve prolapse (MVP) and regurgitation, a cardiac phenotype seldom observed in TBRS." (PMID 39902084, 2024).
mucositis (1 paper, 2023). Mucositis is inflammation and damage of the mucous membranes lining the mouth and other parts of the gastrointestinal (GI) tract. "We conclude that the DNMT1 methylation profile is associated with the post-mucositis period and that the genetic and epigenetic profiles of DNMT3A and DNMT3B are associated with creatinine levels." (PMID 37372315, 2023).
muscle atrophy (1 paper, 2014). The loss of muscle tissue due to inactivity or disease. "The role of Dnmt3a in Fn14 expression has been supported by our findings that overexpression of Dnmt3a inhibits the expression of Fn14 and attenuates denervation-induced muscle atrophy." (PMID 24478779, 2014).
myelodysplastic/myeloproliferative syndrome (1 paper, 2020). "For TET2 and SRSFP95H mutations, myeloid bias was associated with CHIP or the initiation of myelodysplastic/myeloproliferative syndrome, whereas for DNMT3A multipotent stem cell origin was described in the context of CHIP." (PMID 32526214, 2020).
nemaline myopathy (1 paper, 2022). Nemaline myopathy (NM) encompasses a large spectrum of myopathies characterized by hypotonia, weakness and depressed or absent deep tendon reflexes, with pathologic evidence of nemaline bodies (rods) on muscle biopsy. "Interestingly, the levels (fold change) of transcript encoding epigenetic enzymes were not impacted in muscles from patients with AD nemaline myopathy and in AD-RYR1-related CCD only, the expression level of DNMT3A was increased (the mean log2-fold change was 1.16 adjusted P = 0.03)." (PMID 36196089, 2022).
nonalcoholic fatty liver disease (1 paper, 2025). "Under HFD, the Dnmt3a+/–-CH group progressed to severe MASLD, with marked hepatitis reflected by high nonalcoholic fatty liver disease activity score and extensive fibrosis." (PMID 41027007, 2025).
nutritional deficiency (1 paper, 2024). "Screening of CHIP-associated genes, particularly TET2, DNMT3A and ASXL1, can be an optional measure in CAR-T manufacturing in some elderly populations presenting CHIP bias, such as immune cytopenia, marrow dysplasia, and nutritional deficiency." (PMID 38191582, 2024).
odontogenic tumor (1 paper, 2021). "However, the mean nuclear positivity for DNMT1, DNMT3A, DNMT3B, and H3K9ac, were, respectively, 65.07, 82.03, 39.56, and 88.37%, representing the first report of these proteins in a malignant odontogenic tumor." (PMID 35048062, 2021).
oesophagus carcinoma (1 paper, 2010). "The present study provides evidence that a SNP in the DNMT3A promoter region may modify the risk of GC but not of oesophagus carcinoma." (PMID 20128888, 2010).
oral lichen planus (1 paper, 2021). Oral lichen planus is a chronic inflammatory oral condition of unknown aetiology characterized by T-cell-mediated chronic immune response and abnormal epithelial keratinization cycle. "For example, DNMT3A and DNMT3B are increased in lip and oral carcinogenesis, and high levels of DNMT1 can also be seen in oral lichen planus." (PMID 35048062, 2021).
osteogenesis imperfecta (1 paper, 2024). Osteogenesis imperfecta (OI) comprises a heterogeneous group of genetic disorders characterized by increased bone fragility, low bone mass, and susceptibility to bone fractures with variable severity. "Osteogenesis imperfecta (OI) mice with ADSCs express high levels of DNMT3A compared to wild-type mice with ADSCs, and their osteogenic differentiation ability and collagen secretion are significantly impaired." (PMID 39015772, 2024).
ovarian serous carcinoma (1 paper, 2012). "In addition, our current study showed that DNMT3a expression was associated with histological type, e.g., ovarian serous carcinoma expressed higher levels of DNMT3a protein." (PMID 22768205, 2012).
pericardial effusion (1 paper, 2024). Fluid collection within the pericardial sac, usually due to inflammation. "The patient in this case report is the first case in which TBRS is complicated with a massive pericardial effusion caused by a novel mutation in the DNMT3A gene, within both the Chinese and international populations." (PMID 39902084, 2024).
periodontal disease (1 paper, 2024). "Our findings that CHIP due to DNMT3A mutations is associated with a higher prevalence and severity of clinically ascertained periodontal disease lack causality and directionality." (PMID 38838669, 2024).
peripheral artery disease (1 paper, 2023). "Compared to TET2 mutation carriers, patients with DNMT3A mutations had significantly less frequently concomitant coronary and peripheral artery disease." (PMID 36680616, 2023).
peritoneal mesothelioma (1 paper, 2022). A benign or malignant mesothelial neoplasm that arises from the peritoneum. "In our cohort, DNMT3A was altered in 4.1% of pleural mesothelioma and in 3.9% of peritoneal mesothelioma cases." (PMID 36138075, 2022).
pituitary tumor (1 paper, 2019). A benign or malignant neoplasm affecting the pituitary gland. "DNMT1 and DNMT3A overexpression has been detected in pituitary tumors." (PMID 31139150, 2019).
pneumothorax (1 paper, 2026). Abnormal presence of air in the pleural cavity. "We report identical twin brothers presenting with spontaneous pneumothoraces in adulthood, leading to a diagnosis of Tatton-Brown-Rahman syndrome (TBRS), a DNMT3A-related overgrowth disorder not previously associated with pneumothorax." (PMID 41741684, 2026).
primary effusion lymphoma (1 paper, 2021). A large B-cell lymphoma located in the body cavities, characterized by pleural, peritoneal, and pericardial fluid lymphomatous effusions and that is always associated with human herpes virus-8 (HHV-8). "For example, in primary effusion lymphoma (PEL), caused by Kaposi’s sarcoma associated herpesvirus (HHV-8), de novo DNA methyltransferase (DNMT3a) is recruited to chromatin by the viral protein LANA." (PMID 34205549, 2021).
primary myelofibrosis (1 paper, 2022). Myelofibrosis with myeloid metaplasia is a myeloproliferative disease with annual incidence of approximately 1 case per 100,000 individuals and age at diagnosis around 60 (an increased prevalence is noted in Ashkenazi Jews). "Gene mutations in epigenetic regulators (ASXL1, TET2, DNMT3A and EZH2) and RNA splicing (U2AF1 and SRSF2) were considered as the additional subclonal mutations and cooperated with the MPN driver mutation (JAK2, MPL or CALR) to play a key role in the pathogenesis of primary myelofibrosis." (PMID 35740649, 2022).
primordial dwarfism (1 paper, 2023). "These links between DNMT3A LoF and overgrowth phenotype, and between GoF variants and primordial dwarfism can be understood intuitively, but the relations between DNMT3A and brain subfunctions are less well understood." (PMID 36814905, 2023).
Pruritus (1 paper, 2025). Pruritus is an itch or a sensation that makes a person want to scratch. "Finaly, JAK2V617F allele burden ≥50% and DNMT3A truncating mutations were associated with pruritus at diagnosis." (PMID 40533498, 2025).
pulmonary arterial hypertension (1 paper, 2023). Pulmonary arterial hypertension (PAH) is a group of diseases characterized by mean pulmonary artery pressure >20 mmHg and elevated pulmonary arterial resistance leading to right heart failure. "We reviewed the regulation and functions of DNMTs, with an emphasis on somatic mutations in DNMT3A, a common cause of clonal hematopoiesis of indeterminant potential (CHIP) that may also be involved in the development of pulmonary arterial hypertension (PAH)." (PMID 37947606, 2023).
recurrent disease (1 paper, 2025). "In this study, the associations between methylation markers (DNMT1, DNMT3A, and DNMT3B) and both locoregional recurrent disease and disease-specific mortality in patients with locally advanced LSCC treated with definitive, curatively intended radiotherapy alone was investigated." (PMID 40507223, 2025).
renal dysfunction (1 paper, 2023). "This differential effect of DNMT3A on the cardiovascular risk of CKD patients and the influence of renal dysfunction on the appearance of CHIP should be studied in future studies." (PMID 37763205, 2023).
retinal degeneration (1 paper, 2014). Degeneration of the retina. "Ultrastructural analysis of photoreceptor nuclear morphology in the rd1 mouse model for RP revealed a severely altered chromatin structure during retinal degeneration that coincided with an increased expression of the DNMT isozyme DNMT3a." (PMID 25476906, 2014).
rheumatic disease (1 paper, 2025). "The development of rheumatic disease was associated with a lower level of DNMT3A in the frailty patients group (p=0.002).Furthermore, in this group, a correlation between appendicular skeletal muscle mass (ASMM) and the expression of ELAVL1 (r=0.59, p=0.026) was observed." (PMID 40034697, 2025).
scoliosis (1 paper, 2026). A congenital or acquired spinal deformity characterized by lateral curvature of the spine. "TBR syndrome is caused by dominant variants in the DNMT3A gene and is characterized by impaired intellectual development, face abnormalities, tall stature, seizures, scoliosis and large head circumference." (PMID 41501857, 2026).
sebaceous adenoma (1 paper, 2017). A benign, well circumscribed neoplasm arising from the sebaceous glands. "Dnmt3a-cKO mice only developed an increase in the percentage of sebaceous adenomas." (PMID 28425913, 2017).
sweet syndrome (1 paper, 2024). "In one report, two VEXAS patients with DNMT3A mutations experienced complete remission of disease-related inflammatory manifestations, including skin conditions such as polychondritis and Sweet syndrome, following azacytidine therapy." (PMID 39598114, 2024).